IDO1 (indoleamine 2,3-dioxygenase 1)
Diseases named in the same sentence as IDO1 in open-access papers (continued):
Sharing a sentence is not in itself a finding about the gene and the disease.
cancer (continued). "IDO1 is highly expressed in various cancer types and associated with poor prognosis." (PMID 33922388, 2021). "Functionally, IDO1 has played a pivotal role in cancer immune escape via catalyzing the initial step of the kynurenine pathway, and overexpression of IDO1 is also associated with poor prognosis in various cancers." (PMID 33883013, 2021). "High IDO1 expression is associated with poor prognosis in a range of cancers." (PMID 33831358, 2021). "Overall, EBV-associated cancers usually are associated with the enhanced expression of IDO1." (PMID 34944437, 2021). "The enhanced production of kynurenine caused by the expression of the tryptophan catabolizing IDO1 enzyme in cancer cells, cancer-derived vesicles and several other immune and stroma cells in the TME has immunosuppressing effects and is a predictor for poor prognosis in different cancer types." (PMID 34041023, 2021). "Moreover, activation of STAT1 has been predicted to also upregulate expression of cancer associated genes such as IDO1 and PTGS2." (PMID 34946170, 2021). "Furthermore, in human cancer cells, IDO1 has been implicated in improving DNA repair and mediating resistance to treatments, such as the PARP inhibitor olaparib, γ-radiation, and the chemotherapeutic agent cisplatin, by production of NAD+." (PMID 34943977, 2021). "IDO1 encodes the well-known immunosuppressive protein indoleamine 2,3 dioxygenase-1, which is currently being explored as a therapeutic target in multiple cancer types." (PMID 32469992, 2020). "IDO1 has been shown to be highly expressed in many cancers and is associated with poor prognosis." (PMID 33511116, 2020). "Overexpression of IDO1 is associated with poor patient survival in several types of human cancer." (PMID 30338242, 2018). "IDO-1 activity has been linked to a poor prognosis for different types of cancer, including CRC33." (PMID 28195169, 2017). "Additional studies encourage the notion that IDO2 may offer some pathogenic support to advanced cancer in certain settings, albeit less widely than IDO1." (PMID 25477879, 2014). "Third, the possibility that IDO2 might contribute to cancer immunosuppression in some settings where it is expressed, including brain, similar to the manner in which IDO1 has been implicated widely." (PMID 25477879, 2014). "Conceivably, chronic inflammation associated with cancer may create immune suppression through the up-regulation of IDO1, but locally in the bone marrow microenvironment and systemically." (PMID 23973990, 2013). "In this way, increased IDO1 activity helps downregulate several inflammatory diseases, but on the other hand, it is also associated with neurologic disorders, and in cancer cells or in host dendritic cells is associated with suppression of effector T-cell responses toward tumors." (PMID 37116709, 2023). "Moreover, the upregulation of IDO1 has been linked with poor prognosis in cancer patients." (PMID 37945606, 2023). "In addition, IDO1 overexpression is associated with poor prognosis in many malignant tumors." (PMID 35187162, 2022). "Altogether, literature shows that IDO1 might play a key role in EBV-associated cancers." (PMID 34944437, 2021). "In addition to cancer models, this may support research on neurodegenerative and infectious diseases, for which a role of IDO1 has also been implicated." (PMID 33584686, 2020). "Second, by targeting a convergent effector mechanism used by all IDO/TDO enzymes, indoximod may prove less sensitive to inherent or acquired resistance that may arise in patients due to IDO1 mutation, IDO1 overexpression or other target bypass mechanisms that heterogeneous cancers evolve." (PMID 30254983, 2018). "Tumors exhibit elevated Kyn metabolism, with IDO1 frequently overexpressed in various cancers, and its expression level is inversely related to patients’ overall survival time." (PMID 41129671, 2026).
cancer (continued). "Numerous IDO1 inhibitors have been introduced into clinical trials as immunotherapeutic agents for cancer treatment to block the Trp–Kyn pathway." (PMID 41262240, 2025). "This regulation is crucial for the establishment of a therapy-refractory phenotype in tumors, highlighting IDO1 as a potential target for therapeutic intervention in cancer immunotherapy." (PMID 40287406, 2025). "IDO1 also indirectly influences non-IDO1-expressing cells through the kyn pathway metabolites and helps in building immune checkpoints in cancer cells." (PMID 41035912, 2025). "The induction of IDO-1 activity corresponding to aging, cancers, diabetes, stress, and inflammation, facilitates tryptophan degradation and negatively impacts muscle fiber." (PMID 40806744, 2025). "While many studies have investigated IDO1 in the context of cancer, research on IDO2 remains relatively limited." (PMID 41035912, 2025). "In summary, these studies highlight IDO-1 as a promising target for PROTAC development to overcome immune suppression in IDO-1 overexpressing cancers." (PMID 41032705, 2025). "The quantitative analyses of the normalized IDO1 protein showed a variable protein increase in response to the type of inhibitor, depending on the cancer cell line." (PMID 41262240, 2025). "Considering the substantial evidence supporting the role of the KYN pathway as a potential underlying mechanism for immune evasion in cancer, key enzymes, particularly, IDO1 have emerged as pharmacological targets of interest for cancer treatment." (PMID 40348885, 2025). "Harden's analysis of cancers found that IDO1 and TDO2 are preferentially upregulated over KYUN, whereas the opposite occurs in pro‐inflammatory environments." (PMID 40103267, 2025). "High-throughput spatial profiling studies have revealed immunosuppressive niches in cancer TMEs, comprising IDO1- and PD-L1–expressing suppressive macrophages, CD8+ T cells, and Tregs." (PMID 40371647, 2025). "Despite the pivotal role of IDO1 in anti‐cancer immunity and the strong pre‐clinical rationale for IDO1 inhibition as an oncological target, clinical trials have not yielded the anticipated success." (PMID 40910376, 2025). "IDO1 is presented across multiple types of cancer, and its expression is upregulated by inflammatory cytokines such as IFN-γ." (PMID 41129257, 2025). "AhR stimulates IL-6–dependent STAT3 signaling, which maintains IDO1 expression and thereby immunosuppression in several human cancers." (PMID 40789452, 2025). "Currently, several clinical phase I and II trials with IDO-1-inhibitors in human cancer are reporting results." (PMID 40475772, 2025). "In cancer, overexpression of IDO1 and TDO2 leads to increased tryptophan degradation, depleting local tryptophan levels and resulting in T cell anergy and immune escape." (PMID 39997327, 2025). "In fact, IDO1 is an important immunotherapy target in cancer due to the induction of anticancer responses, and IDO1 inhibitors (e.g., indoximod) have been evaluated in clinical trials." (PMID 40848064, 2025). "By promoting carcinogenesis and aiding in the development of immunological checkpoints in cancer, IDO1 renders APCs tolerogenic." (PMID 41035912, 2025). "We developed an immunomodulatory nanoplatform combining a STING agonist and an IDO1 inhibitor to boost T-cell responses and reduce Treg infiltration, thereby proposing a combinatorial nanotherapy against immune-evasive cancers." (PMID 41129257, 2025). "IDO1 expression is commonly upregulated in various cancers, and it plays a key role in creating an immunosuppressive microenvironment." (PMID 40299564, 2025). "To address this question, we studied GAPDH heme transfer to the client protein indoleamine 2,3-dioxygenase 1 (IDO1), whose enzyme activity is heme-dependent and regulates mammalian immune responses and cancer progression." (PMID 40609793, 2025).
cancer (continued). "The emergence of IDO1 inhibitors and the sensitizing effect of gut microbiota on immunotherapy present new directions for cancer treatment." (PMID 40103267, 2025). "The exploration of IDO1 as a therapeutic target in cancer immunotherapy has evolved from early small-molecule inhibitors to advanced protein degradation strategies." (PMID 40894232, 2025). "Extensive research has demonstrated that targeting IDO1 can inhibit the tryptophan metabolism of cancer cells, suggesting IDO1 as a viable drug target for cancer therapy." (PMID 39973065, 2025). "IDO1 is frequently overexpressed in various cancer types, where it exerts a potent immunosuppressive effect within the TME." (PMID 40452814, 2025). "We identified IDO1, a well-documented enzyme involved in cancer immune evasion, as a potentially synergistically induced HH-IL6 target gene in human HaCaT keratinocytes." (PMID 39962447, 2025). "IDO1, with an important role in regulating the innate and adaptive immune response, is overexpressed in many types of cancers, including CRC45." (PMID 39779996, 2025). "It displays immunomodulating and antineoplastic activities by inhibiting IDO1, leading to decreased kynurenine levels and restoring proliferation and activation of immune cells suppressed in many cancers." (PMID 41035912, 2025). "Since its discovery in the 1960s, inhibiting IDO1 has emerged as a promising approach to rejuvenate cancer immunosurveillance." (PMID 40287406, 2025). "Indoleamine 2,3-dioxygenase 1 (IDO1) has emerged as a critical immunometabolic regulator in cancer, orchestrating immunosuppression through its rate-limiting catabolism of tryptophan to kynurenine." (PMID 40894232, 2025). "Given its central role in these processes, IDO1, the rate-limiting enzyme in tryptophan degradation, has emerged as a key therapeutic target in cancer immunotherapy." (PMID 40666095, 2025). "IDO1 and tryptophan metabolites, including kynurenine itself, are immunosuppressive in a variety of cancers." (PMID 40449595, 2025). "While over 20 small-molecule IDO1 inhibitors have entered clinical trials for various cancers, their variable efficacy has underscored the need for improved target engagement strategies and better patient selection biomarkers." (PMID 40894232, 2025). "All three inhibitors significantly reduced Kyn levels in the cancer cell line supernatants with a fold change (FC) <0.5 versus the control cells, indicating the efficacy of the IDO1 catalytic inhibitors in all the tested cancer cell lines." (PMID 41262240, 2025). "The three different IDO1 inhibitors were tested in different human cancer cell lines that share an endogenous and constitutive expression of the IDO1 enzyme, catalyzing the conversion of Trp to Kyn." (PMID 41262240, 2025). "Several studies have already proven the potential role of IDO1 inhibitors in the treatment of cancer." (PMID 40137109, 2025). "To explore the role of IDO1 in mediating resistance, we thus established IDO1-overexpressing MC38 tumors, and, in parallel, we included an Ido1-knockout cancer model to examine the effects of our binary design rationale." (PMID 41129257, 2025). "The development of PROTACs represents a groundbreaking advancement in IDO1-targeted cancer immunotherapy, offering a fundamentally distinct mechanism of action compared to conventional small-molecule inhibitors." (PMID 40894232, 2025). "Through critical analysis of their mechanisms of action and therapeutic potential, we provide insights into optimizing IDO1-targeted strategies for cancer immunotherapy." (PMID 40894232, 2025). "Bin1 can downregulate IDO1 through STAT1 and NF-κB-dependent pathways; however, in many cancers, Bin1 is inactivated, supporting IDO1 overexpression." (PMID 41035912, 2025). "The application of PROTAC technology to IDO1 inhibition has not only provided new tools for cancer immunotherapy but has also established a framework for targeting other immunometabolic pathways in oncology." (PMID 40894232, 2025).
cancer (continued). "Unfortunately, some IDO-1 inhibitors are terminated or paused in clinical trials due to a lack of improvement in progression-free and overall survival in cancer patients." (PMID 40806744, 2025). "In contrast, treatment with 7k reduced the expression levels of AhR, AhRR, and IDO-1 in kynurenine-stimulated cancer cells in a dose-dependent manner." (PMID 41155994, 2025). "IDO1 inhibitors, in particular, have undergone extensive evaluation in clinical trials, demonstrating potential for enhancing the efficacy of existing cancer therapies." (PMID 41332472, 2025). "IDO1 contributes to immune suppression by promoting cancer cell proliferation, migration, and invasion." (PMID 41035912, 2025). "To further validate our kynurenine-responsive genetic circuit, we transduced 4T1 cancer cells with either an ido1-expressing lentiviral vector or an empty vector, creating the 4T1-IDO1 and 4T1-EV cell lines, respectively." (PMID 40512849, 2025). "These unfavorable outcomes highlight the unresolved aspects of IDO1 function in cancer immune suppression." (PMID 40332338, 2025). "These preliminary observations confirm the importance of blocking the dual activity of IDO1 in cancer." (PMID 41262240, 2025). "We also analyzed in the same samples the IDO1 protein level by Western blot, and surprisingly, we observed an increased level of IDO1 protein in all the cancer cell lines exposed to EPA, LIN, and NAV." (PMID 41262240, 2025). "Indoximod (D-1MT, NLG8189) has garnered widespread attention due to its role in immune evasion by cancer cells and is one of the most studied IDO1 inhibitors in preclinical studies." (PMID 39973065, 2025). "Following these results, clinical trials using IDO1 inhibitors in other cancer types were also discontinued." (PMID 40554511, 2025). "Researchers have confirmed the critical role of IDO-1 in various biological processes, including those involving infectious viruses and bacterial diseases, transplantation, and cancers." (PMID 40710094, 2025). "Enrichment of cells expressing IDO1 and PD-L1 is a common feature of chronic inflammatory diseases and cancer, underscoring the role of myeloid–T cell interactions in pathological TMEs." (PMID 40371647, 2025). "Since the discovery of IDO-1 overexpression and its immunosuppressive role in different cancers, inhibitors have been developed." (PMID 41032705, 2025). "IDO1 has emerged as a significant target for cancer therapy due to its critical role in tryptophan degradation." (PMID 40075563, 2025). "The unfavorable prognosis of IDO1-positive cancers is likely often attributed to the combined influence of several of the IDO1-induced processes." (PMID 39061522, 2024). "In conclusion, the anti-cancer effects of QFM combined with PD-1 inhibitor are mainly through inhibiting activation of STAT1/IDO1-mediated tryptophan-kynurenine pathway and down-regulating expression of PD-1." (PMID 38882349, 2024). "The aim of this review was to investigate the mechanisms that are currently considered to participate in IDO1-mediated immune suppression and its impact on cancer growth." (PMID 39371092, 2024). "In recent years, cancer immunotherapy has emerged as a groundbreaking approach, and the inhibition of IDO1 has been explored as a potential strategy." (PMID 39351094, 2024). "IDO1 is being used as an adjuvant medication in a growing number of ongoing clinical trials in conjunction with other cancer therapy methods due to the poor efficacy of single medicines." (PMID 38539263, 2024). "It is interesting to note that while IDO1 seems to contribute to immune escape in cancer, its presence in interstitial foci in transplanted kidneys is associated with an increased risk of rejection." (PMID 39064305, 2024). "While clinical evaluation of selective TDO inhibitors for cancer treatment is still to be awaited, various IDO1 inhibitors have already entered clinical development, frequently in combination with immune checkpoint blockade." (PMID 39211039, 2024).
cancer (continued). "For instance, a comprehensive analysis of the predictive value and immunological role of the IDO1 gene in pan-cancer revealed that IDO1 has abnormal expression in several malignancies and is related to the prognosis of various types of cancer." (PMID 39064305, 2024). "Generally, cancers exhibit a high expression of IDO1 and TDO2 to catabolize tryptophan, generating abundant KYN." (PMID 38347841, 2024). "The emerging findings showed that indoleamine 2,3-dioxygenase 1 (IDO1) is overproduced in highly tumorigenic self-renewing repopulating cancer cells." (PMID 38474359, 2024). "In a phase I clinical trial evaluating a dual IDO1/TDO2 inhibitor in a small cohort of patients with various cancer types, treatment was well tolerated to the point that a MTD was not determined." (PMID 38451784, 2024). "In terms of OS, IDO1 expression was unfavorable in the five cancers (GBM, KIRP, LAML, LGG, and UVM) where IDO1 expression was low, and gene expression was positively correlated with survival." (PMID 38539263, 2024). "IDO1 is a challenging protein to drug, yet it plays a crucialrole as a target in cancer immunotherapy." (PMID 38990186, 2024). "Herein, we investigated IDO1 transcript expression across cancers and clinical outcome correlations." (PMID 38632994, 2024). "By targeting and decreasing the metabolic crosstalk between cancer cells and immune cells, particularly through dual inhibition of IDO1 and TDO2, new therapeutic strategies can be developed to overcome drug resistance and improve patient outcomes." (PMID 39911818, 2024). "Indoleamine 2, 3-dioxygenase 1 (IDO1) is highly expressed on many cancers, being a pivotal enzyme in the pathway of tryptophan metabolism." (PMID 38685033, 2024). "Among them, although NTRC 3883-0 can inhibit IDO1, the acceptable dose for cancer patients makes clinical use less meaningful." (PMID 39253578, 2024). "The production of these enzymes including IDO1 appears to derive primarily from cancer cells and MDSCs, resulting in more immunosuppressive TME." (PMID 38632994, 2024). "Inhibition of indolamine-2,3-dioxygenase 1 (IDO1) has been proposed as a promising strategy for cancer immunotherapy; however, it has failed in clinical trials." (PMID 39351094, 2024). "In both cancer and neurodegeneration, the IDO1/TDO2-KYN-AHR axis is central to metabolic alterations and immune evasion, highlighting its significance as a therapeutic target." (PMID 39911818, 2024). "Another three MGPs paired with VHL, a cancer driver gene frequently mutated in RCC, support the inhibition of indoleamine 2,3-dioxygenase 1 (IDO1) as a drug target, which was previously attempted." (PMID 38468344, 2024). "A similar but natural phenomenon occurs in human cancer cells, in which proteome-wide Trp-to-Phe substitutions arise from Trp depletion by IFNγ-mediated IDO1 induction." (PMID 39154912, 2024). "IDO1 and PD-L1 are co-expressed in a number of cancers, and preclinical studies have demonstrated the additive or synergistic effects of combined inhibition of IDO1 and PD-L1." (PMID 39054491, 2024). "In contrast, no clinical evidence is available for anti-LAG3, anti-TIGIT, anti-BTLA, anti-ICOS and anti-IDO1 antibodies in MSI-H cancers, but clinical trials are ongoing." (PMID 38254772, 2024). "In conclusion, it is necessary to explore the impact of IDO1 on cancer and search for novel IDO1 inhibitors and alternative therapeutic approaches to target IDO1." (PMID 39408347, 2024). "Numerous studies have demonstrated that targeting the immunometabolic enzyme indoleamine 2,3 dioxygenase 1 (IDO1) is highly expressed in multiple types of human cancer." (PMID 38539263, 2024). "The abnormal hyperexpression of PDL1 and IDO1 of cancer cells plays a crucial role in immune tolerance and immune evasion." (PMID 38302412, 2024). "IDO1 catabolism of tryptophan to kynurenine inhibits T-cell-mediated immune responses and IDO1 expression has been shown to be elevated in many cancers." (PMID 39054467, 2024).